STAT1 (signal transducer and activator of transcription 1)
Diseases named in the same sentence as STAT1 in open-access papers (continued):
Sharing a sentence is not in itself a finding about the gene and the disease.
tauopathy (4 papers, 2021 to 2023). Neurodegenerative disorders involving deposition of abnormal tau protein isoforms (tau proteins) in neurons and glial cells in the brain. "In a subsequent step, overall feature importance assessment highlighted IER- and cellular immunity-related TFs (FOS, JUN, NFATC2/3, STAT1) as most useful in predicting the tauopathy or Ctrl state." (PMID 35976433, 2022). "Combined with our published data, we conclude that inhibition of NMDAR expression by activation of STAT1 and inactivation of STAT3 may be a general mechanism of the synaptic and cognitive deficits in tauopathies." (PMID 33859760, 2021).
type 2 diabetes (4 papers, 2024 to 2025). "Additionally, individuals with both type 2 diabetes (T2D) and PD exhibit increased levels of the pro-inflammatory transcription factors STAT1 and IRF1 along with a decrease in JMJD3 expression in circulating monocytes." (PMID 39315124, 2024).
viral myocarditis (4 papers, 2015 to 2024). Myocarditis that is caused by an infection with a viral agent. "The study discovered that STAT1 were activated in DCM, moreover, activation of STAT1 transcription factor precedes up-regulation of coxsackievirus-adenovirus receptor (CAR) during viral myocarditis." (PMID 38321374, 2024). "The activation of the transcription factor STAT1, which is prominent in our model, is also known to be an early event in viral myocarditis." (PMID 26539991, 2015). "Meanwhile, STAT1 phosphorylation of PAR2 overexpressed CFs has been shown to be significantly decreased following PAR2 and TLR3 agonist stimulation, suggesting that PAR2 negatively regulates TLR3-dependent IFN-β production and promotes viral myocarditis." (PMID 36827455, 2023).
acne (3 papers, 2014 to 2025). An inflammatory process of the sebaceous glands which is characterized by comedones, nodules, papules and/or pustules on the skin. "Similar findings were observed in the German cohort, since STAT1 a positive regulator of Th1 development was induced, and the CXCR3 ligands CXCL9, CXCL10 and CXCL11, were overexpressed in lesional acne skin." (PMID 25153527, 2014).
acute pancreatitis (3 papers, 2014 to 2024). An acute inflammatory process that leads to necrosis of the pancreatic parenchyma. "Phosphorylation of STAT1 is the critical step initiating pulmonary inflammation in LPS, gastric acid aspiration, or acute pancreatitis-induced ALI." (PMID 24692852, 2014).
acute promyelocytic leukemia (3 papers, 2014 to 2023). An aggressive form of acute myeloid leukemia (AML), characterized by arrest of leukocyte differentiation at the promyelocyte stage, due to a specific chromosomal translocation t(15;17) in myeloid cells. "In acute promyelocytic leukemia (APL), RIG-I together with STAT1 activates ISG-critical genes including ISG15, which is testified as a crucial factor to affect myeloid differentiation." (PMID 37662910, 2023). "Pretreatment with valproic acid (VPA) suppressed the transcription of IFN-stimulated anti-viral genes, such as signal transducers and activators of transcription 1 (STAT1), protein kinase R (PKR) and promyelocytic leukemia (PML), thereby increasing HSV gene expression, propagation and cytotoxicity." (PMID 32992948, 2020). "To determine whether HDACi affect the expression and activity of STAT1 in leukemic cells, we treated NB4 acute promyelocytic leukemia (APL) cells with butyrate, a naturally occurring HDACi." (PMID 24810717, 2014).
allergic rhinitis (3 papers, 2021 to 2026). Inflammation of the nasal mucous membranes caused by an IgE-mediated response to external allergens. "Previous literature has reported that IFITM3 overexpression can increase the STAT1 expression, and STAT1 is involved in the pathogenesis of SEA‐induced allergic rhinitis and IgE production, but the exact mechanism remains unclear." (PMID 39412083, 2024).
Autoimmune Polyendocrinopathy-Candidiasis-Ectodermal Dystrophy (3 papers, 2019 to 2025). "Endocrine autoimmunity is a defining feature of Autoimmune Polyendocrinopathy-Candidiasis-Ectodermal Dystrophy (APECED) and IPEX syndrome, but was also prominent in patients with STAT1 gain-of-function variants." (PMID 41394846, 2025).
brain inflammation (3 papers, 2020 to 2024). "Therefore, DJ-1 may prevent excessive STAT1 activation and reduce the risk of brain inflammation." (PMID 39062793, 2024). "We conclude that Stat1 serves as an inducible checkpoint for NSC self-renewal that is upregulated during chronic brain inflammation leading to decreased self-renewal." (PMID 37663126, 2023).
Burkitt lymphoma (3 papers, 2016 to 2023). A rare form of malignant mature B-cell non-Hodgkin lymphoma. "Downregulation of STAT1 by c-MYC overexpression observed in the current study is also detected in Burkitt’s lymphoma, supporting the concept that immune escape of tumor cells could be promoted by activation of a cellular oncogene." (PMID 27198694, 2016).
chordoma (3 papers, 2013 to 2025). Chordomas are rare malignant tumors arising from embryonic remnants of the notochord in axial skeleton. "In addition, all chordoma cell lines expressed IRF9, which forms a complex with activated STAT1 and STAT2 that stimulates the transcription of ISGs." (PMID 40901948, 2025). "By comparing methylation patterns of blood from healthy individuals and chordoma patients we found 20 significantly differentially methylated genes; 15 hypermethylated in chordoma (for example RASSF1, KL, RARB, HIC1, and FMR1) and 5 hypomethylated (HSD17B4, BAZIA, STAT1, NEUROGL, and JUP)." (PMID 23533570, 2013).
chronic hepatitis B (3 papers, 2010 to 2021). "For example, up-regulated miR-146a can reduce NK cell-mediated cytotoxicity and the expression of TNF-α and IFN-γ by targeting STAT1, and depresses T-cell immune function in chronic hepatitis B (CHB) patients by inhibiting STAT1." (PMID 34017248, 2021). "In addition, the differences of STAT-1 expression in liver tissue of patients with chronic hepatitis B who had different responses to antiviral therapy with IFN-α were also investigated in this study." (PMID 20957108, 2010).
complement deficiencies (3 papers, 2019 to 2025). "Similarly, patients with complement deficiencies or STAT1 mutations should be monitored for severe bacterial infections." (PMID 31362757, 2019).
Cryptosporidium infection (3 papers, 2024 to 2025). "This research sheds light on potential therapeutic strategies that target the TLR4/STAT1 pathway to combat Cryptosporidium infections effectively." (PMID 39902829, 2025). "Several studies have demonstrated that Cryptosporidium infection leads to the production of types I, II, and III IFN in vivo, each of which can act on IEC to signal through the transcription factor signal transducer and activator of transcription 1 (STAT1)." (PMID 38718306, 2024).
dementia (3 papers, 2012 to 2020). Loss of intellectual abilities interfering with an individual's social and occupational functions. "The glutaminase C (GAC, one isoform of GLS1) mRNA levels in HIV associated-dementia (HAD) individuals correlate with STAT1 (p<0.01), IFN-α (p<0.05) and IFN-β (p<0.01)." (PMID 22479354, 2012). "Using the mRNA from the same sets of brain tissues, we found that STAT1 mRNA levels were significantly increased in HAD patients compared to HIV serum negative individuals and HIV serum-positive patients without dementia (p<0.05)." (PMID 22479354, 2012). "To further investigate the clinical relevance of STAT1 and GLS1 to HAD, we analyzed STAT1 and GLS1 mRNA levels from post-mortem brain tissue collected from HAD patients, HIV serum-positive patients without dementia, and HIV serum negative individuals." (PMID 22479354, 2012).
dermatomyositis (3 papers, 2017 to 2021). Dermatomyositis (DM) is a type of idiopathic inflammatory myopathy characterized by evocative skin lesions and symmetrical proximal muscle weakness. "Compared with typical dermatomyositis patients, the degree of IFN-related pathways activation in MDA5 positive patients was lighter, accompanied by a lower-activating state of STAT1, leading to a down-regulation of NOS2 expression in Th1 macrophages." (PMID 34966600, 2021).
dermatophytosis (3 papers, 2015 to 2022). A common fungal infection of the stratum corneum of the skin, hair, or nails by a dermatophyte. "Extensive dermatophytosis with hyperkeratotic dermatophytosis confined to the stratum corneum may also occur in patients with chronic mucocutaneous candidiasis associated with STAT1 gain-of-function mutations." (PMID 29376922, 2015). "In humans, monogenic inborn errors of immunity can cause severe dermatophytosis, including autosomal recessive mutations in caspase recruitment domain family member 9 (CARD9) and autosomal dominant mutations in signal transducer and activator of transcription 1 (STAT1)." (PMID 35157719, 2022).
diabetic retinopathy (3 papers, 2024 to 2025). "Intravenous administration of HucMSC-derived EVs in mice with diabetic retinopathy (DR) showed improved inflammatory response and reduced oxidative damage through the miR-17-3p-mediated targeting of signal transducer and activator of transcription 1 (STAT1)." (PMID 38343632, 2024).
emphysema (3 papers, 2015 to 2025). "STAT1 is a known inducer of emphysema-associated processes such as apoptosis and inflammation; however, its precise role in emphysema and COPD development has not been established." (PMID 25962837, 2015). "Results described here further support a potential role of STAT1 in emphysema development." (PMID 25962837, 2015). "In alignment with these observations, our findings identified an upregulation of RAGE and STAT1 genes in lung tissue, alongside increased expression levels of RAGE, p-JAK2, p-STAT1, p-STAT3 and p-STAT5 in pulmonary mDCs in a smoking-induced mouse model of emphysema." (PMID 40951546, 2025).
glomerulosclerosis (3 papers, 2015 to 2021). A hardening of the kidney glomerulus caused by scarring of the blood vessels. "STAT1 was most strongly activated along Bowman’s capsule epithelial cells and in some cells along the periphery of glomeruli, a region where small capillaries become scarred in older kidneys (glomerulosclerosis)." (PMID 26678048, 2015). "On the other hand, STAT1 was most strongly activated along Bowman’s capsule epithelial cells and in some cells along the periphery of glomeruli, accelerating the progression of glomerulosclerosis, thus having a deleterious effect on kidney physiology and function." (PMID 29643988, 2018). "Inflammatory cytokines such as IFN γ, IL-6, and TNF overactivated STAT1, STAT3, and NF-κB transcription factors to promote glomerulosclerosis and renal interstitial fibrosis." (PMID 34194519, 2021). "In summary, the regions showing activation of STAT1, STAT3 and NFκB during aging suggests a possible role for these transcription factors in the progression of glomerulosclerosis and renal interstitial fibrosis during aging." (PMID 26678048, 2015).
Hashimoto disease (3 papers, 2012 to 2025). "Our immunohistochemical data demonstrated that STAT1 transcription factor is abundantly expressed in the nuclei of oncocytes, also known as Hürthle cells, Askanazy cells, or oxyphilic cells, which are a hallmark of Hashimoto's disease, but not exclusively confined to this entity." (PMID 22527947, 2012).
helminth infections (3 papers, 2019 to 2021). "Here, we used STAT1−/− mice to investigate the role of this transcription factor during a helminth infection caused by the cestode Taenia crassiceps and show that STAT1 is a central molecule favoring susceptibility to this infection." (PMID 34684235, 2021). "In order to analyze the role of STAT1 in the immunoregulation of a helminth infection, we used a mouse model of cysticercosis caused by the cestode T. crassiceps." (PMID 34684235, 2021). "In contrast, the role of STAT1 in helminthic infections is understudied." (PMID 34684235, 2021). "Moreover, the impact of helminthic infections on modulating the STAT1/IFN-γ signaling pathway is reflected in coinfections with viruses, where the presence of helminths reactivates latent viral infections." (PMID 34684235, 2021). "Here, we uncover a novel role for STAT1 by showing that mice lacking this transcription factor do not completely develop M2 macrophages during a helminth infection." (PMID 34684235, 2021). "STAT1 is one of the most important players in the IFNγ signaling important for the classic activation of macrophages, which is typical in bacterial infections but not in helminth infections." (PMID 30783117, 2019).
hemorrhage (3 papers, 2021 to 2024). Loss of blood from the vascular compartment to the exterior or into nonvascular body space as a result of rupture or severance of the blood vessels. "For example, CUR alleviates neuronal apoptosis and neuroinflammation induced by cerebral haemorrhage by inhibiting the JAK1/STAT1 pathway and inhibits IL-1β-induced chondrocyte apoptosis by activating autophagy and inhibiting the NF-κB pathway." (PMID 39000093, 2024). "To evaluate the protective effect provided by anti-S1-RBD IgG against DENV infection in vivo, we evaluated DENV infection-induced hemorrhage in STAT1-/- mice." (PMID 36045680, 2022). "In this study, by employing Stat1-/- mice and applying intradermal route of inoculation, we investigated whether infecting mosquito alters the hemorrhage-induction potential of DENV in the mammalian host." (PMID 34449772, 2021). "Our study showed that Stat1-/- mice are responsive to gradient titers of DENV2 and the severity of hemorrhage development correlates with the titers of the viral inocula delivered through the intradermal route." (PMID 34449772, 2021). "Exploiting the sensitivity of Stat1-/- mice to low dose of DENV2 delivered intradermally, we showed that DENV2 collected in infected mosquito saliva (msq-DENV2) induced more severe hemorrhage in mice than their culture counterpart." (PMID 34449772, 2021).
Intracranial aneurysms (3 papers, 2014 to 2023). "Intracranial aneurysms have been reported in patients with both STAT3 loss-of-function (LOF) and STAT1 GOF." (PMID 36884218, 2023).
leukopenia (3 papers, 2020 to 2025). "In contrast to the STAT1−/− mouse model which displays leukopenia, the STAT2−/− hamster exhibits an increase in white blood cells similar to the Hu-NSG-SGM3 humanized mouse model upon infection." (PMID 32704046, 2020).
lung squamous cell carcinoma (3 papers, 2017 to 2025). "Silencing of RFWD3 in lung squamous cell carcinoma (LUSC) H2170 cells also led to upregulation of p‐STING, p‐TBK1, p‐IRF3, and p‐STAT1." (PMID 41117130, 2025).
Lymphadenopathy (3 papers, 2019 to 2022). Enlargement (swelling) of a lymph node. "All of the four patients with the T437N STAT1 mutation experienced lymphadenopathy." (PMID 31114772, 2019). "We observed significantly up-regulated Stat1 mRNA levels in lymph nodes, spleen, kidney, lung, and liver in Regnase-3−/− mice with lymphadenopathy." (PMID 31126966, 2019). "The fourth sibling had neither the STAT1 variant nor lymphadenopathy or malignancy." (PMID 31114772, 2019).
male infertility (3 papers, 2022 to 2026). The inability of the male to effect fertilization of an ovum after a specified period of unprotected intercourse. "All of these results indicated that MKRN2-regulated STAT1 is involved in the process of male infertility." (PMID 36967804, 2023). "Thus, we wonder how to evaluate the regulatory mechanism between MKRN2 and STAT1/SIX4/TNC to figure out the novel mechanism of MKRN2 in male infertility." (PMID 36967804, 2023). "In this study, we found a new regulatory mechanism between MKRN2 and STAT1/SIX4/TNC, which is a novel mechanism of MKRN2 in regulating male infertility." (PMID 36967804, 2023). "In this study, we plan to address: (a) the role of MKRN2 in male infertility; (b) whether MKRN2 regulates the expression level of STAT1; and (c) how MKRN2 induces the expression levels of SIX4 and TNC by the transcription factor EBF transcription factor 2 (EBF2)." (PMID 36967804, 2023). "In addition, members of the JAK-STAT pathway, TYK2, STAT1 and STAT4, have been shown to be active in human sperm, indicating that defects in the JAK-STAT pathway in sperm may be related to male infertility." (PMID 36003498, 2022).
memory impairment (3 papers, 2013 to 2022). "Thus, activation of STAT1 might be a key step in age-associated memory impairment." (PMID 25431548, 2014). "Importantly, inactivated JAK2/STAT1 due to GJ-4 was found to improve memory impairment in focal CI/reperfusion in rats." (PMID 35508616, 2022). "Interestingly, mice that lack STAT1 show enhanced memory performance and are resistant to memory impairment induced by Aß peptides injected into the hippocampus." (PMID 25431548, 2014). "In conclusion, our data showed that HPB242 can protect Tg2576 mice from memory impairment through inhibition of NF-κB and STAT1/3, which could result in the inhibition of Aβ1-42 accumulation by attenuating β-secretase activity." (PMID 23289709, 2013).
Mendelian susceptibility to mycobacterial diseases (3 papers, 2023 to 2024). "The hallmark of AD STAT1 deficiency is Mendelian susceptibility to mycobacterial diseases (MSMD), and individuals with this disease are susceptible to invasive infections caused by weakly virulent mycobacteria." (PMID 39840042, 2024).